STK11 (serine/threonine kinase 11)
Diseases named in the same sentence as STK11 in open-access papers (continued):
Sharing a sentence is not in itself a finding about the gene and the disease.
tumor (continued). "In the LUAD-LUSC transition model driven by expression of KRASG12D along with STK11 depletion, tumours have been found to originate from SCGB1A1+ Club cells and SFTPC+SCGB1A1+ BASCs, as assessed by allograft assays following 3D organoid culture." (PMID 34354223, 2021). "Serine-threonine kinase LKB1 (STK11, also referred to as Liver Kinase 1), is a tumor suppressor that negatively regulates mTORC1 activity." (PMID 34208071, 2021). "LKB1 (also known as serine-threonine kinase 11, STK11) is a tumor suppressor and functions in the AMPK (adenosine monophosphate-activated protein kinase) pathway necessary for cell metabolism, homeostasis, and autophagy." (PMID 34733787, 2021). "ULK1/2 has been linked to diverse oncogenic or tumor-suppressive signalling cascades (e.g., KRASG12D/Copper, PI3K/AKT/mTOR, FAK/RhoA, STK11/liver kinase-B1 [LKB1]) that are engaged in pathogenesis of solid tumors from various types 50-52." (PMID 34345207, 2021). "While loss of STK11 and PTEN significantly reduced overall survival (32.71 or 46.72 vs. 58.45 months, respectively), mutations in any of the four tumor suppressors negatively affected disease-free and progression-free survival." (PMID 33738287, 2021). "In contrast, miRNA-451 can promote cell proliferation and metastasis in PDAC by down-regulating CAB39 (Calcium binding protein 39), a tumor suppressor upstream of STK11 (serine-threonine kinase 11)." (PMID 34368146, 2021). "Liver kinase B1 (also known as STK11) is a tumor suppressor gene that is inactivated in many malignant tumors." (PMID 34124017, 2021). "Latency until tumor growth and metastasis development were shortened compared to the STK11-wild-type (WT) counterpart." (PMID 34831355, 2021). "Authors concluded that SIK1 and SIK3 were highly responsible for STK11 tumor suppressing functions and can therefore be important targets to mediate these pathways for therapeutic reasons." (PMID 34781949, 2021). "A large analysis, testing 1343 NSCLC tumor samples with NGS, showed a significant association between EGFR and PI3KCA or CTNNB1 mutations and between KRAS and STK11 mutations." (PMID 32365882, 2020). "Accordingly, the STK11 promoter was found to be demethylated or partially methylated in the majority of tumor samples; only two tumor tissues were found to be methylated." (PMID 32911741, 2020). "The upstream tumor suppressors STK11/LKB1 (serine/threonine kinase 11) and their target, AMPK, contribute to HSCs quiescence by directly controlling mitochondrial autophagy, ULK1 and FIS1 mediated." (PMID 32486249, 2020). "STK11 is a protein kinase regulating energy metabolism and proliferation of the cell and is recognized as a key enzyme of tumor suppression." (PMID 31845182, 2020). "We were not able to find a correlation between methylation and expression levels of STK11 in tumor samples through our MSP methylation status analysis." (PMID 32911741, 2020). "The liver kinase B1 (LKB1, encoded by STK11) is a tumor suppressor function as a highly conserved serine/threonine kinase." (PMID 32532965, 2020). "In contrast, when KRAS mutations are associated with STK11/LKB1 deficiency, the tumor landscape is cold and associated with reduced PD-L1 expression." (PMID 33276569, 2020).
tumor (continued). "This includes HeLa cells, the first human cells ever to be established in culture, which were derived from a case of cervical cancer in which analysis of the original tumour biopsies revealed a large deletion in the STK11 gene." (PMID 33375416, 2020). "The tumor with low STING and immune gene expression shows a high frequency of serine-threonine kinase 11 (STK11) mutation." (PMID 33643304, 2020). "While analyzing matched samples of adjacent healthy tissue and tumor counterparts, the same pattern of subexpression of STK11 is observed." (PMID 32911741, 2020). "Characteristic of the early discoveries of tumor‐suppressing genes, STK11 was discovered through studies that pinpointed truncating germline mutations in a gene residing on chromosome 19p in multiple individuals affected by PJS." (PMID 30548122, 2019). "The serine/threonine kinase gene (STK11/LKB1) is a substantial tumor suppressor gene, which acts as an energy metabolic sensor and is involved in cell polarity regulation and mediation of apoptosis." (PMID 30975222, 2019). "LKB1 (STK11) is a well-characterized tumor suppressor that governs diverse cellular processes, including cell growth, polarity, and metabolism." (PMID 31212916, 2019). "The STK11 gene plays a key role in cell proliferation via many targets, where a requirement has been suggested for the tumor suppressor function of this kinase and/or STK11 catalytic activity." (PMID 30975222, 2019). "MTOR overactivation has been also explained to be related to hamartomatous tumor growth, when STK11 inactivation is occurred in mic." (PMID 30975222, 2019). "The major cause of this disease is germ line mutations in the STK11 (serine threonine kinase 11) gene, also known as the LKB1, which is a tumor suppressor gene and is located on chromosome 19p13.3 (Chae and Jeon, 2014)." (PMID 29743854, 2018). "Different mutations were also observed in STK11 in patient 1 (a missense mutation p.K78N in tumour 1 and a nonsense mutation p.Q37X in tumour 2) and in EGFR in patient 4 (p.L858R in tumour 1 and p.S229C in tumour 2)." (PMID 27767028, 2016). "STK11 is a known tumor suppressor that regulates cell polarity by remodeling the actin cytoskeleton." (PMID 27014907, 2016). "Liver kinase B1 (LKB1), also known as serine/threonine protein kinase 11 (STK11), functions in many types of cancer as a tumor suppressor." (PMID 27266881, 2016). "Three genes, including STK11, SFRP1 and CREB3L1, were involved in tumor-associated signaling pathway, and selected for further RT-PCR analysis." (PMID 27385214, 2016). "In contrast to the MS cohorts, we detected a significant association of STK11-SNP with TCCP comorbidities in the control group, consistent with the known role of LKB1 as a tumor suppressor." (PMID 25694554, 2015). "Immunohistochemistry analysis of the tumor showed decreased expression of STK-11 as compared to one of the patient's hamartomatous polyps." (PMID 25649062, 2015). "It is well known that gene STK11, also known as LKB1, encodes a member of the serine/threonine kinase family that regulates cell polarity and functions as a tumor suppressor." (PMID 26083494, 2015). "A G > C transversion at the 5′ splice site of exon 4 of STK11 was also identified in both components of tumor #5." (PMID 26068980, 2015). "STK11 is in turn a tumor suppressor and regulator of energy homeostasis through the activation of AMP-activated protein kinase (AMPK)." (PMID 24759943, 2014).
tumor (continued). "We also observed low impact alteration in KIT and STK11 exclusively in the tumor group which resulted from base transversions." (PMID 25404506, 2014). "The tumor suppressor gene LKB1, also known as serine/threonine protein kinase 11 (STK11), encodes a serine/threonine protein kinase that has multiple cellular functions, including tumor suppression, cell cycle regulation, and promotion of apoptosis." (PMID 25178656, 2014). "Liver Kinase B1 (LKB1, also called STK11) is frequently mutated in NSCLC and is thought to act as a tumor-suppressor gene." (PMID 23936763, 2013). "LKB1 (a tumor suppressor, Serine/threonine kinase 11) has a role in maintaining cellular energy levels (ATP/AMP ratio), phosphorylating AMPK in response to a decline in the cellular ATP/AMP ratio." (PMID 22669258, 2013). "The gene that is responsible for causing PJS is the tumor suppressor gene, STK11/LKB1, which is located on the short arm of chromosome 19 (19p13.3)." (PMID 24179492, 2013). "Liver Kinase B1 (LKB1, also called STK11) was initially identified as the tumour suppressor gene mutated in the inherited Peutz-Jeghers cancer syndrome, an autosomal dominant genetic disorder." (PMID 22412893, 2012). "The tumor suppressor LKB1 (also known as Stk11) is an evolutionarily conserved serine/threonine protein kinase that has a broad range of cellular functions, including tumor suppression, cell polarity, cell-cycle regulation, and promotion of apoptosis." (PMID 22353783, 2012). "Loss of the normal allele has been observed in polyps from patients with PJS, and loss of heterozygosity (LOH) has been noted to occur in some tumor tissues, suggesting that STK11 is a tumor suppressor gene." (PMID 18495044, 2008). "The major AMPK-activating kinase was identified as LKB1/STK11, a tumor suppressor that causes cancer predisposition in humans." (PMID 17150096, 2006). "Although previous studies have shown that tumor tissue-based STK11, KEAP1, and CDKN2A/B mutations are adverse prognostic factors, we further confirm that ctDNA-based STK11, KEAP1, and CDKN2A can predict unfavorable outcomes in patients with non-metastatic NSCLC." (PMID 41491583, 2026). "Loss of STK11 disrupts AMPK signaling, leading to unchecked mTOR activation, metabolic reprogramming, angiogenesis, and epithelial-mesenchymal transition, fostering tumor progression and immune evasion." (PMID 42187558, 2026). "Co‐occurring mutations with smoking‐related canonical mutations, such as KRAS, STK11, and KEAP1, are common in patients with SMARCA4 mutations, and up to 44% of these patients exhibit a smoking‐related co‐mutation signature and a high tumor mutational burden." (PMID 41577374, 2026). "Lastly, the mechanisms underlying the adverse prognostic impact of STK11, KEAP1, and CDKN2A mutations, currently inferred from tumor RNA-seq data and bioinformatic analyses, remain to be experimentally validated in future in vivo and in vitro fundamental research." (PMID 41491583, 2026). "Interestingly, KEAP1/STK11 co-mutations occurred more frequently than KRAS/KEAP1 or KRAS/STK11 co-mutations, suggesting a functional synergy between NRF2- and LKB1-regulated pathways in tumor progression." (PMID 40427178, 2025). "STK11 and KEAP1 mutations confer worse outcomes with immunotherapy among patients with KRASMUT but not among patients with KRASWT, provoking an accrual of neutrophils with T cell suppressive effects and tumor-promoting cytokines." (PMID 41009806, 2025). "In LUAD, STK11 and KEAP1 mutations have been implicated in promoting aggressive tumor behavior." (PMID 40427178, 2025). "This implies that the STK11 mutant tumor may partially regulate the host immune system through modulating cytokine signaling." (PMID 41051525, 2025).
tumor (continued). "The STK11 gene, also known as LKB1, encodes a protein serine/threonine kinase that behaves as a tumour suppressor and is also responsible for multiple biological and cellular processes, including metabolism maintenance, cell polarity, proliferation, and migration." (PMID 40650126, 2025). "Mutations in STK11 create a non-T cell-inflamed tumour microenvironment (TME), which reduces responsiveness to immune checkpoint inhibitors (ICIs)." (PMID 40277912, 2025). "Additionally, efforts to modulate the inflammatory landscape through IL-6-neutralising or neutrophil-depleting antibodies show promise in reversing the immunosuppressive effects of STK11-driven tumours." (PMID 40277912, 2025). "GSEA further confirmed the enrichment of immune-related pathways in Stk11-KO cells, suggesting the hypothesis that STK11 modulates tumor–immune interactions." (PMID 41051525, 2025). "Similarly, in STK11-deficient NSCLC mouse models, large numbers of PMN-MDSCs have been identified both within the locally tumor microenvironment and systemically in peripheral blood." (PMID 41051525, 2025). "To explore whether TSPAN7 can influence tumor cell proliferation through STK11, we treated TSPAN7‐overexpressing CRC cells with radicicol, a known STK11 inhibitor." (PMID 41031049, 2025). "The well-established tumor-suppressive functions of RKIP (PEBP1) and LKB1 (STK11) suggest that their expression, either independently or in concert, may influence cancer progression through effects on the tumor microenvironment (TME)." (PMID 40806276, 2025). "Understanding how PEBP1/STK11 co-expression may interfere with the function and properties of tumor MM is essential for gaining deeper insights into tumor metabolism and its potential therapeutic implications." (PMID 40806276, 2025). "Tumor-infiltrating CD11b+Ly6C−Ly6G+ PMN-MDSCs were also increased in the Stk11-KO group." (PMID 41051525, 2025). "The study includes two groups: one with tumor PD-L1 expression of less than 1% regardless of STK11 mutation status, and the other with PD-L1 expression of greater than or equal to 1% with STK11 co-mutation." (PMID 40303413, 2025). "STK11 (LKB1) loss and KEAP1 loss both confer a more aggressive, therapy-resistant tumor biology." (PMID 40723270, 2025). "STK11 serves as a tumour suppressor in lung, cervical, and many other cancers." (PMID 40791513, 2025). "Unlike EGFR‐mutant tumours, which exhibit relatively uniform biology and high therapeutic sensitivity, KRAS‐mutant NSCLC is characterised by profound molecular heterogeneity, divergent co‐mutational profiles (e.g., STK11, KEAP1), and dynamic crosstalk with the tumour microenvironment (TME)." (PMID 41025426, 2025). "STK11 mutations were also associated with a lack of PD-L1 expression and were enriched for negative PD-L1 staining, whereas tumours with high PD-L1 (>50%) were less frequently mutated for STK11." (PMID 40647497, 2025). "However, knowledge of deactivating variants in tumour suppressors can also have important implications for diagnostics; for instance, both CHEK2 and STK11 variants are difficult to assess in the context of hereditary cancers." (PMID 41152984, 2025). "A particularly strong and uniform negative correlation was evidenced between the co-expression of these genes and the transcription of several major matrix metalloproteinase (MMPs) and PEBP1/STK11 levels, indicating a suppressive effect on local tumor invasion." (PMID 40806276, 2025).
tumor (continued). "Here we provide direct evidence of derivation of SCC of the thyroid from PTC, based on a unique combination of likely pathogenic mutations in KEAP1, STK11 (LKB1), and RB1 found in both tumor components, along with loss of one copy of chromosome 11 and additional somatic mutations in the SCC tumor." (PMID 40600748, 2025). "The notable exception of this trend was observed in COAD, READ, and STAD, where CXCR3 displayed a positive correlation with PEBP1/STK11 expression, highlighting the complex and context-dependent interplay between PEBP1/STK11 and chemokine-mediated immune regulation in the tumor microenvironment." (PMID 40806276, 2025). "The STK11 alterations are associated with a cold tumor immune microenvironment characterized by low or no PD-L1." (PMID 39045411, 2024). "The loss of STK11/LKB1 promotes the production of IL-6, which recruits neutrophils, inhibits recruitment of T cells, and is associated with high levels of T cell exhaustion markers such as PD-1 and TIM-3, and decreased expression of PD-L1 on tumor cells." (PMID 38903504, 2024). "Although the anti-tumor role of metformin has been widely studied, its impact on tumor metabolism of STK11 mutant NSCLC and the involved crucial metabolites were unknown." (PMID 39308524, 2024). "Notably, it was reported that STK11 mutations were related to an immunologically “cold” TME, characterized by low PD-L1 expression and decreased tumor-infiltrating CD8+ lymphocytes." (PMID 39308524, 2024). "Loss of STK11 function or mutations in LKB1 have been identified in 10%–20% of NSCLC and are believed to confer inferior survival outcomes and relative ICI resistance in advanced NSCLC when compared to wild-type tumours." (PMID 39749035, 2024). "Although the prognostic role of STK11 mutations is well-established and their role on ICI responsiveness is emerging, the mechanisms through which these mutations alter tumor immunogenicity is unknown." (PMID 39113608, 2024). "Our previous work demonstrated that metformin promoted the anti-tumor effect of PD-1 inhibitor in H460 cells, which have a nonsense STK11 mutation naturally, but not in Axin1-/- H460 cells." (PMID 39308524, 2024). "The recent discovery of mutations in DICER1, STK11 and FOXL2 genes has improved our understanding in addition to the approach to sex cord stromal tumours and can serve as diagnostic and prognostic markers and may assist in risk stratification in the future." (PMID 39430077, 2024). "Previous research has showed that expression of STK11 was positively correlated with intertumoral infiltration of cluster of differentiation CD3+, CD4+, and CD8+ cells, demonstrating patients with high levels of STK11 would have better immune conditions for tumor control." (PMID 38736875, 2024). "STK11 adnexal tumours may be considered epithelial type due to the acinar and tubular formation, as well as the expression of broad-spectrum cytokeratin." (PMID 38376618, 2024). "As tumour cells express epithelial, sex cord stromal and mesothelial markers, STK11 adnexal tumour may be of sex cord stromal, epithelial or mesothelial origin; a Wolffian origin has also been suggested." (PMID 38376618, 2024). "However, when the tumor molecular profile of the patient was made available, an STK11 alteration was detected, indicating that resistance to treatment was highly likely in this case." (PMID 39045411, 2024). "Other studies targeting this challenging STK11-low tumour group are currently recruiting." (PMID 39749035, 2024).